ESCO2 (establishment of sister chromatid cohesion N-acetyltransferase 2)
Diseases named in the same sentence as ESCO2 in open-access papers (continued):
Sharing a sentence is not in itself a finding about the gene and the disease.
embryonic carcinoma (1 paper, 2022). "ESCO2 overexpression enhanced the differentiation of neural progenitor cells and P19 embryonic carcinoma cells." (PMID 35990266, 2022).
Fanconi anemia (1 paper, 2012). Fanconi anemia (FA) is a hereditary DNA repair disorder characterized by progressive pancytopenia with bone marrow failure, variable congenital malformations and predisposition to develop hematological or solid tumors. "This patient had features of both Fanconi Anemia (associated with other DNA helicases involved in DNA damage repair, XPD, and FANCJ) and RBS, in which ESCO2 is mutated." (PMID 22988450, 2012).
gastric tumor (1 paper, 2023). "Among autophagy genes in the Reactome database, PRMT1 was negatively correlated with genes such as ATG9A, DYNC1H1, EPAS1, PINK1, TSC1, TUBB6, and ULK1 in gastric tumor tissues (STAD-TCGA) and positively correlated with HMMR, ESCO2, CHAC2, and NUDT6 (STAD-TCGA)." (PMID 37564212, 2023).
Hyperinsulinemia (1 paper, 2024). An increased concentration of insulin in the blood. "Additionally, hyperinsulinemia inhibited the transcriptome required for cell cohesion MELK, CDCA7, ESCO2, mitotic spindle assembly KIF15, SGO1, and AURKB, and kinetochore formation KNL and NDC80." (PMID 39768214, 2024).
kidney cancer (1 paper, 2025). Primary or metastatic malignant neoplasm involving the kidney. "ESCO2 is significantly upregulated in kidney cancer tissues, and ESCO2 knockdown inhibits cancer cell growth, invasion, and migration by regulating the AKT/mTOR pathway." (PMID 40657363, 2025).
lung adenocarcinoma (1 paper, 2021). A carcinoma that arises from the lung and is characterized by the presence of malignant glandular epithelial cells. "Whether ESCO2 promotes the malignant progression of lung adenocarcinoma by regulating gene transcription and its specific regulatory mechanisms, this will be the focus of our further research." (PMID 33573689, 2021).
ovarian carcinoma (1 paper, 2021). A malignant neoplasm originating from the surface ovarian epithelium. "Particularly, we examined if ANPEP (from EC2), CASP14 and CLEC2B (from EC3), CADM3 and NRBP2 (from EC4), and SPC25, ESCO2, and GTSE1 (from EC5) are responsible for ovarian cancer cell proliferation by the cell viability assay." (PMID 34459128, 2021). "Additionally, our study identified a number of novel markers, such as CASP14, CLEC2B, CADM3, NRBP2, SPC25, ESCO2, and GTSE1, which are upregulated in a cluster‐specific manner and critical for ovarian cancer cell proliferation and migration." (PMID 34459128, 2021).
pancreatic cancer (1 paper, 2022). "In our analysis, the CN gains of ESCO2 and HDAC10 were found to be risk factors for colorectal and pancreatic cancer, respectively." (PMID 35422864, 2022).
paraganglioma (1 paper, 2024). A benign or malignant neoplasm arising from paraganglia located along the sympathetic or parasympathetic nerves. "However, the ESCO2 expression value did not significantly change in KICH, PAAD, pheochromocytoma and paraganglioma (PCPG), or READ." (PMID 38605349, 2024).
sarcoma (1 paper, 2022). A usually aggressive malignant neoplasm of the soft tissue or bone.
seminoma (1 paper, 2009). A radiosensitive malignant germ cell tumor found in the testis (especially undescended), and extragonadal sites (anterior mediastinum and pineal gland). "ESCO2 (establishment of cohesion 1 homolog 2) is tightly correlated with BRCA1-dependent and various cell-type specific carcinogenesis, and DAPP4 pluripotent factor is enriched in seminomas." (PMID 20015385, 2009).
cancer (24 papers, 2009 to 2025). A tumor composed of atypical neoplastic, often pleomorphic cells that invade other tissues. "From this analysis we determined that there were more MR events, in multiple cancer types, in ESCO2 deficient tumors compared to proficient tumors." (PMID 35994499, 2022). "We surveyed The Cancer Genome Atlas (TCGA) database for prevalence of genetic alterations in key sister chromatid cohesion (SCC) factors and found that ESCO2 was most frequently deleted or mutated gene in many cancers." (PMID 35994499, 2022). "To determine if human cancers that have ESCO2 deficiencies also have higher MR rates, we analyzed TCGA data to define all LOH loci that maintained a 2N copy number, this would exclude regional deletions or whole chromosome deletion, as well as amplifications." (PMID 35994499, 2022). "However, the underlying mechanism of ESCO2 upregulation in cancer development remains incompletely understood." (PMID 40657363, 2025). "Higher expression of ESCO2 was significantly associated with better survival in five cancer types." (PMID 34136387, 2021). "Given the role for mutated ESCO2 (homolog of ECO1) in human birth defects, this study highlights the complex nature through which mutation of ESCO2, and defects in ESCO2 regulation, may promote developmental abnormalities and contribute to various diseases including cancer." (PMID 33373396, 2020). "In recent years, research on the role of ESCO2 in cancer has gradually increased, primarily focusing on its impact on DNA repair and chromosome stability." (PMID 40708936, 2025). "Among these genes, sister chromatid cohesion acetyltransferase 2 (ESCO2) has emerged as an important target in cancer research." (PMID 41053890, 2025). "This review article summarizes recent research progress regarding ESCO2 in malignant tumors, aiming to identify a novel target for their treatment." (PMID 41053890, 2025). "In previous studies, ESCO2 was identified as a potential target for cancer therapy, as it is a pivotal protein in the cell division process." (PMID 40657363, 2025). "The analysis showed that ESCO2 expression was upregulated in most cancer tissues except LAML, ACC and PCPG." (PMID 38605349, 2024). "In conclusion, ESCO2 is a possible pan-cancer biomarker and oncogene that can reliably predict the prognosis of cancer patients." (PMID 38605349, 2024). "The GSEA results also indicate that ESCO2 is involved in cancer inflammation control, including IL2 STAT5 signaling, which raises the possibility that ESCO2 also controls the tumor immune microenvironment." (PMID 38605349, 2024). "As described in the context, current researchers consider ESCO2 an excellent therapeutic target as an oncogene that promotes cancer development." (PMID 38605349, 2024). "Establishment of sister chromatid cohesion N-acetyltransferase 2 (ESCO2) was identified as an effective target for cancer therapy, which is a pivotal protein in the cell division process." (PMID 38605349, 2024). "Using the TCGA database, our work found that ESCO2 is substantially expressed in the tumor tissue of most cancer types." (PMID 38605349, 2024). "Depletion of ESCO2 in CRC cells leads to the disruption of 53BP1-MDs ring-like structure and causes cancer cells to become hypersensitive to chemotherapeutic drugs." (PMID 37377435, 2023). "All these data suggest ESCO2 plays a crucial role in the proliferation and metastasis of various human cancers." (PMID 37968576, 2023). "We report widespread and consistent changes in alternative splicing of cancer-associated genes including CENPE, ESCO2, CKAP2, MELK, ASPH and CD164 in both HeLa and PC3 cells." (PMID 33846420, 2021). "Here, we used three public databases (Oncomine, Gene Expression Omnibus [GEO], The Cancer Genome Atlas [TCGA]) to analyze ESCO2 (establishment of cohesion 1 homolog 2) expression in LUAD." (PMID 33573689, 2021). "In recent years, ESCO2 has been identified as an essential factor in cancer progression in multiple human cancers." (PMID 33573689, 2021).
cancer (continued). "However, ESCO2 has been shown to inhibit cancer metastasis in colorectal cancer by reducing MMP2 expression." (PMID 40657363, 2025). "ESCO2 was significantly elevated in tumor tissues in several malignancies, and ESCO2 knockdown could inhibit cancer cell proliferation, invasion, and migration." (PMID 40657363, 2025). "Furthermore, ESCO2 seemed to participate in the modulation of cancer inflammation, such as IL2 STAT5 signaling." (PMID 38605349, 2024). "ESCO2 expression was raised in most cancers, supporting its oncogene function." (PMID 38605349, 2024). "First, we evaluated the ESCO2’s mRNA expression value in 33 cancers by TCGA and GTEx databases." (PMID 38605349, 2024). "We gathered RNA sequencing profiles of cancer types where ESCO2 could significantly affect patients’ overall survival times to examine the ESCO2 oncogenic role in malignancies." (PMID 38605349, 2024). "Moreover, ESCO2 expression positively correlates with tumor stage and tumor size in several cancers, including LIHC, KIRC, KIRP and LUAD." (PMID 38605349, 2024). "Some of these genes, including ESCO2, may be passengers, deleted purely based on their proximity to tumor suppressors, while others may represent novel genes with a role in cancer formation and progression." (PMID 35994499, 2022). "ESCO2 is a cohesion regulator that contributes to cancer cell proliferation." (PMID 33846420, 2021). "Therefore, together with other research data, our data indicate that ESCO2 plays a key role in the proliferation and metastasis of many types of human cancer." (PMID 33573689, 2021). "ESCO2 has not previously been implicated in human cancers, but its function certainly suggests it could be important, and it appears to be at one of the sub-peaks of this deletion region." (PMID 35994499, 2022). "To demonstrate the influence of ESCO2 on cancer growth, metastasis, and colony formation, we generated aESCO2-FLAG construct, where the FLAG tag (six amino acids) was fused to the full-length ESCO2 transcript." (PMID 33573689, 2021). "It has been reported that ESCO2, CDCA2 and CENPA are cell cycle-related genes involved in cancer progression." (PMID 29642861, 2018). "ESCO2 has the ability to knock down MMP2, thus inhibiting migration of cancer cells." (PMID 35409426, 2022). "ESCO2 is essential for establishment of SCC and is often deleted/altered in human cancers." (PMID 35994499, 2022). "ESCO2 histone acetyltransferase curbs MMP2 and also encourages apoptosis in cancer cells." (PMID 35096000, 2021).
tumor (14 papers, 2018 to 2025). "Our results show that ESCO2 expression was positively associated with tumor stage and size in LIHC, KIRC, KIRP and LUAD." (PMID 38605349, 2024). "To decipher if ESCO2 loss is a driver of tumorigenesis, we wanted to determine if ESCO2-deficient animals are tumor predisposed." (PMID 35994499, 2022). "Further, our analysis of the TCGA data strongly supports that ESCO2 loss in tumors is associated with elevated mitotic recombination and elevated tumor suppressor inactivation." (PMID 35994499, 2022). "On the other hand, ESCO2 was shown to regulate mTOR in tumor cells; therefore, STAT1 may also be associated with ESCO2’s molecular activity." (PMID 37968576, 2023). "ESCO2 exhibits complex and heterogeneous expression patterns across various types of malignancies and tumor progression stages." (PMID 41053890, 2025). "On the contrary, ESCO2 expression was higher in lower tumor stages than in higher tumor stages in COAD." (PMID 38605349, 2024). "We discovered that ESCO2 expression was significantly increased in advanced tumor stage in several malignancies, including KICH, KIRC, KIRP, LUAD, and LIHC." (PMID 38605349, 2024). "In this study, we found that ESCO2 mediates tumor progression potentially by affecting STAT1 signaling." (PMID 37968576, 2023). "Meanwhile, ESCO2 was reported to regulate tumor progression by forming a macromolecular complex to interfere with signaling transductions." (PMID 37968576, 2023). "As our data indicated that ESCO2-silenced cells showed significantly inhibited tumor cell growth, we sought to identify ESCO2’s interactome with a focus on cell migration and/or proliferation-related pathways." (PMID 37968576, 2023). "To determine if the increased LOH frequency was only associated with tumor suppressor gene or genes under a selective pressure for LOH, we surveyed the entire genome for LOH frequencies in ESCO2 wild-type and deficient tumors." (PMID 35994499, 2022). "In contrast, we found that several lysine acetylation regulators also showed features of tumor suppressors, such as ESCO2." (PMID 34136387, 2021). "Here, comparison of tumor-adjacent normal lung tissue via analysis of the Oncomine, GEO and TCGA datasets showed that ESCO2 mRNA and protein expression levels were upregulated in LUAD tissues." (PMID 33573689, 2021). "According to qRT‐PCR analysis, the expressional pattern were diverse although the ESCO2 was highly regulated in three tumor cell lines compared with the human tubular epithelial cells HK2 cells (P < .01)." (PMID 31944408, 2020). "We accessed The Cancer Genome Atlas (TCGA) database to evaluate the ESCO2 expression levels in tumor tissues, including 32 normal tissues and 289 tumor tissues." (PMID 31944408, 2020). "In the ACC and PCPG, the ESCO2 expression levels of the tumor and normal tissues were similar." (PMID 38605349, 2024). "Furthermore, ESCO2 participated in mitosis, the cell cycle, DNA damage repair, other processes, and tumor immune infiltration." (PMID 38605349, 2024). "In LIHC, KIRC, LGG, and PAAD, ESCO2 expression was positively correlated with tumor grade." (PMID 38605349, 2024). "Similarly, ESCO2 was significantly expressed in proliferating T cells, but we observed a higher expression of ESCO2 in tumor cells and macrophages as well." (PMID 38605349, 2024). "Together, these data suggest that ESCO2 is involved in tumor cell migration." (PMID 37968576, 2023). "Together, these data suggest that ESCO2 is critical in regulating tumor growth in vivo." (PMID 37968576, 2023). "The deletions are defined as at least 50% reduction of gene copy number, suggesting that ESCO2 may be a haploinsufficient tumor suppressor gene." (PMID 35994499, 2022).
tumor (continued). "To demonstrate ESCO2 expression in LUAD tissues, we performed qPCR and western blotting on five LUAD tissues and the corresponding non-tumor (NT) tissue samples; the results showed that ESCO2 mRNA and protein expression levels werelower in the NT tissues than in the LUAD tissues." (PMID 33573689, 2021). "Furthermore, ESCO2 stable silencing decreased the tumor growth and pulmonary metastasis of the NCI-H1975 cells in vivo." (PMID 33573689, 2021). "Therefore, we next explored the ESCO2’s role in the anti-tumor immune response." (PMID 38605349, 2024). "Therefore, research into ESCO2’s function in the tumor immune microenvironment is essential." (PMID 38605349, 2024). "We then queried whether the ESCO2 expression level is involved in HPC patients’ tumor progression." (PMID 37968576, 2023). "Together, these findings highlighted the STAT1’s tumor-promoting role in HPC and indicated its involvement in ESCO2-mediated HPC development." (PMID 37968576, 2023). "Among these genes, PLK1, CDC25C, ESCO2, AXIN2, TREX2, ALKBH2, and MC1R were upregulated in tumor tissues, whereas IGF1 and ESR1 presented downregulation." (PMID 35484177, 2022). "Herein, we conducted this work to confirm the function of ESCO2 in RCC carcinogenesis and figure out if it will provide secondary help for tumor diagnosis." (PMID 31944408, 2020). "Furthermore, it has been demonstrated that ESCO2 can promote the methylation of histone H3 at lysine 9 (H3K9), which drives tumor growth in vivo by forming macromolecular complexes." (PMID 37968576, 2023). "Here, we showed that depletion of ESCO2 reduced tumor growth and increased the γH2AX level in the absence of chemotherapy reagents, suggesting that the endogenous ROS-induced DSB damage cannot be properly repaired in ESCO2-depleted cells." (PMID 37377435, 2023). "Collectively, these data suggest that depletion of ESCO2 inhibits tumor growth in the absence of chemotherapy agents by affecting endogenous DNA damage repair and cell cycle arrest." (PMID 37377435, 2023). "Additionally, four genes (i.e., COL6A1, SYDE1, ESCO2, and GIPC1) were differentially expressed between tumor and normal tissues." (PMID 34149809, 2021). "Therefore, it is reasonable to speculate that ESCO2 may interact with STAT1 to inhibit and impair its tumor suppressor activity." (PMID 37968576, 2023). "In addition, CENPL, ESCO2, and CLSPN also serve important roles in tumor progression." (PMID 34556022, 2021).
genetic disorder (2 papers, 2009 to 2018). "RBS is due to the mutations in the ESCO2 gene that also regulates cohesin, whereas AGS is an independent genetic disorder due primarily to mutations in the JAG1 gene, a member of the Notch signaling pathway." (PMID 19468298, 2009).
ESCO2 also shares sentences with these, for which no sentence is quoted: Cornelia de Lange syndrome (5 papers); chronic atrial and intestinal dysrhythmia (2); hypopharyngeal carcinoma (2); lung squamous cell carcinoma (2); Alpha-thalassemia (1); ascariasis (1); Azoospermia (1); CHOPS syndrome (1); fibrosis (1); intellectual disabilities (1); microcephaly (1); oral cancer (1); pheochromocytoma (1); preeclampsia (1); prostate carcinoma (1); psoriasis (1); renal cell carcinoma (1).